STAT3 (signal transducer and activator of transcription 3)
Diseases named in the same sentence as STAT3 in open-access papers (continued):
Sharing a sentence is not in itself a finding about the gene and the disease.
cancer (continued). "It targets different proteins such as EGFR, COX-2, STAT3, ERK, JNK, Akt, p38, caspases, Bax etc. which regulate different processes in cancer cells like survival, proliferation, invasion, metastasis, chemoresistance, radiation resistance, and cell death." (PMID 31759370, 2019). "Iron directly binds CDK1, which is upregulated in several cancers, thereby promoting JAK1 phosphorylation and activation of STAT3 signaling to promote colorectal carcinogenesis." (PMID 30931929, 2019). "Immune system associated pathways, such as interferon alpha and gamma signaling, IL6 JAK STAT3 signaling, TNFA signaling through NFKB and MTORC1 signaling, were found to be upregulated in both ASD and 55%, 55%, 41%, 41% and 63% of cancer types, respectively." (PMID 31007884, 2019). "JAK overactivation has been implicated in tumorigenesis, and persistent activation of STAT3, and to a lesser extent STAT5, has been shown to increase proliferation, survival, angiogenesis, and metastasis in a variety of human cancers." (PMID 31681603, 2019). "As detailed in the reviews and articles of this Special Issue of Cancers, deregulated activation of STAT3 and STAT5 contributes to various cancers in many ways." (PMID 31752278, 2019). "Therefore, Jak-STAT3 signaling pathway represents a valid target for anticancer drugs and effective block of its activation could be a promising strategy for discovery and development of novel anticancer agents in cancer therapy." (PMID 31354479, 2019). "We believe that these knowledge and new combination therapies are applicable to many other cancer types, particularly given that PDLIM2 repression and RelA and STAT3 activation are common in human cancers." (PMID 31757943, 2019). "For example, both capsaicin and apigenin are major bioflavonoids present in several vegetables that are consumed daily and have anti-inflammatory and anticancer properties via the interruption of multiple cancer-related pathways including PI3K/AKT and STAT3." (PMID 31830143, 2019). "Napabucasin, a small molecule compound which was developed to inhibit several pathways in cancer stem cell-like cells, exerts at least some of its therapeutic activity through binding to the SH2 domain of STAT3 and, consequentially, suppresses STAT3 activity." (PMID 30857125, 2019). "Proliferation and apoptosis of cancers are regulated by multi-signaling pathways, such as PI3K/AKT/mTOR, MAPK/ERK, and STAT3." (PMID 31178739, 2019). "The increased expression of HSP90 promotes the activation of oncogenic protein kinases, which are JAK2/STAT3, PI3K/AKT, and MAPK, and facilitates the cancer cell progression." (PMID 31878360, 2019). "STAT3 is activated by adipokine-induced JAK phosphorylation and regulates various processes related to cancer development and progression." (PMID 31212761, 2019). "This demonstrates that the Stat5/3loxP/loxP mouse is functional and can be readily used to model STAT3 and STAT5A/B double inhibition in cancer and other disease-experimental mouse models." (PMID 31443474, 2019). "Hence, our findings strongly suggest that PTC-209 mediates its anti-cancer effect on several cancer cell lines, at least in part, through downregulation of STAT3 pathway and do not exclude the possible involvement of other signaling pathways in the inhibition of STAT3 phosphorylation by PTC-209." (PMID 31695609, 2019). "In terms of cancer stemness, IL6/STAT3 signaling has been found to induce expression of the cancer stem cell (CSC) marker CD133 via interaction of STAT3 with NF-κB and HIF-1α in HCC." (PMID 31731457, 2019).
cancer (continued). "In BCC, the interaction of HH/GLI and pro-inflammatory IL6/signal transducer and activator of transcription-3 (STAT3) signaling synergistically regulates common GLI-STAT3 target genes and promotes cancer proliferation." (PMID 31878932, 2019). "In a phase I trial of the STAT3 inhibitor OPB-51602, EGFR-mutant NSCLC patients were likely to obtain better response among the patients of various cancer types." (PMID 31137841, 2019). "The STAT3/STAT5 signaling dysregulates a plethora of cellular processes in EOC, which results in uncontrolled cancer cell proliferation, induction of angiogenesis, promotion of metastasis factors, and suppression of host immune response." (PMID 31861720, 2019). "We found that LDOC1 deficiency led to reinforcing a reciprocal loop of IL-6/JAK2/STAT3, through which LDOC1 mediates the cancer progression." (PMID 30634502, 2019). "STAT3 and STAT5 proteins are of particular interest in cancer research, as their hyperactivation was reported in processes ranging from inflammation and autoimmunity to infection and cancer." (PMID 31817042, 2019). "STAT3 activation also regulates the expression of VEGF and human cancer angiogenesis and metastasis." (PMID 31287013, 2019). "Taken together, our results suggest that danazol exerts a CS effect by inhibiting the STAT3 pathway in MDR cancer cells and thus provides a possible solution for MDR cancers." (PMID 31406162, 2019). "We found that enrichment for STAT3 targets in basal type UBC, as measured by transcriptome analysis is paralleled by a significantly increased fraction of cancer cells expressing pSTAT3+ in basal-type UBC." (PMID 31438567, 2019). "Previous studies have shown that STAT3 and STAT5 can serve as therapeutic targets, and their expression is a predictive biomarker of drug resistance in cancers." (PMID 31601188, 2019). "It involves JAK/STAT3-Akt signaling pathways in the suppression of the extracellular matrix protein CCN5, which acts as an anti-invasive element in cancer." (PMID 31380268, 2019). "Autocrine production of IL-33 has been suggested to contribute to human cancer cell survival, migration and resistance to chemotherapy, through the up-regulation of anti-apoptotic proteins including Bcl-2, and via ST2/STAT3." (PMID 31535033, 2019). "Molecular docking mechanism of GA was performed through binding simulation analysis for various cancer signaling pathway, viz., Bcl-2, Pl3K, NF-κB, Akt/PKB, and Stat-3." (PMID 31357897, 2019). "Increasing lines of evidence indicate that nuclear-factor kappaB (NF-κB) and signal transducer and activator of transcription 3 (STAT3) activation can lead to survival, angiogenesis, and metastasis of the cancer cells." (PMID 31443458, 2019). "Cancer cells (mPLRB9 from KIC, KPC‐M09 from KPC and BMFA3 from KPfC) were incubated with TGFβ‐CM and subjected to Western blotting for STAT3 signaling." (PMID 31609088, 2019). "Context-dependent activities of STAT3 and STAT5 in solid human cancers justify detailed molecular studies that will clarify the specific molecular mechanisms of action of these two cancer genes." (PMID 31557897, 2019). "Increased activation of AKT-mTOR increases the phosphorylation levels of STAT3, leading to CCL2 expression and suppressing cancer immune reaction activation." (PMID 31781676, 2019). "Acting via STAT3 stimulation and up-regulation, G-CSF presents itself as a very attractive target for NB CSC elimination and for increasing the potential long-term cancer-free survival in children." (PMID 31191243, 2019). "Our earlier observations showed elevated STAT3 signaling in HPV-infected precancer and cancer lesions and its functional contribution in cervical carcinogenesis." (PMID 31487312, 2019).
cancer (continued). "On the contrary, STAT3 can activate miR-21 and miR-181b-1 via PTEN and CYLD, which is the switch linking inflammation to cancer in MCF10A cells." (PMID 31803051, 2019). "LDHB transcription is also directly stimulated by the signal transducer and activator of transcription 3 (STAT3), a key tumorigenic driver in many cancers." (PMID 31035592, 2019). "Recently, several studies have shown that various transcriptional factors, such as STAT1, STAT3, BRD4, NF-kB, PI3K/AKT/mTOR, and MEK1/2/ERK1/2, promoted PD-L1 transcription in cancer cells." (PMID 31818309, 2019). "Previous studies have revealed that FOXM1 expression is driven primarily by the Hedgehog, Ras/MEK/MAPK, signal transducer and activator of transcription 3 (STAT3), and wnt/β-catenin in different cancer cells." (PMID 30782607, 2019). "STAT3 and STAT5 activity is often elevated in aggressive subtypes of cancer and serve as prognostic indicators." (PMID 31684144, 2019). "Recent evidence suggests a crucial role of signal transducer and activator of transcription 3 (STAT3) is selectively induced and maintain a pro-carcinogenic inflammatory microenvironment during the cancer progression." (PMID 31028131, 2019). "Increasing evidence have indicated that the STATs, particularly STAT1, STAT3, and STAT5 play critical roles in various cancer progressions and have been identified as potential therapeutic targets." (PMID 30944204, 2019). "In line with an important role of EGFR and IL6 signaling in GLI-driven cancers, genetic and pharmacological inhibition of EGFR and IL6/JAK2/STAT3 signaling, respectively, interferes with GLI-driven tumor growth." (PMID 30991683, 2019). "This included the EMT-inducing zinc-finger E-box-binding homeobox factor (ZEB2) and the STAT3 target MMP2, which enhances the degradation of extracellular matrix proteins and cancer cell invasion." (PMID 30645971, 2019). "Activated STAT3 and STAT5 regulate the expression of VEGF and increased angiogenesis in a variety of cancer, including EOC." (PMID 31861720, 2019). "Although many studies reported that AXT suppresses the expression of NF-κB and STAT3, transcription factors of MYC, to abrogate carcinogenesis in various cancer cells, the detail regulatory mechanisms are still elucidated." (PMID 31263239, 2019). "Other research groups also found that in cancer cells the EGFR inhibitors erlotinib and dacomitinib can activate the interleukin-6 (IL6) / JAK / STAT3 signaling pathway, thereby leading to drug resistance." (PMID 30674340, 2019). "Thus, JAK2/STAT3 could serve as a potential target for cancer therapy." (PMID 31540495, 2019). "In this context, it has been demonstrated that both c-Fos and c-Jun binding to the miR-21 promoter region increases after treatment with PMA, and that STAT3 and AKT signal transduction pathways can induce miR-21 gene promoter activity in cancer cells." (PMID 31427899, 2019). "The constitutive activation of STAT3 and STAT5 play vital roles in the proliferation, survival, apoptosis, and angiogenesis of cancer cells." (PMID 30872582, 2019). "Immunofluorescence analysis showed increased expression and nuclear co-localization of FRA1, phosphorylated STAT3, and NANOG protein in the cancer samples when compared with adjacent (para-carcinoma) normal tissues." (PMID 30804456, 2019). "In this study, we found that JAK2/STAT3 signaling was preferentially enriched in the CSC population and required for their cancer-repopulating capacity." (PMID 31511084, 2019). "We found that STAT3 activation (phosphorylation) and LGR5 mRNA levels were individually induced by EGF, revealing that EGFR is capable of exacerbating cancer stemness properties; this finding is consistent with that of a previous study." (PMID 30068339, 2018).
cancer (continued). "We are the first to report that adipocyte-derived adipokines activate PLOD2 expression via activation of the JAK/STAT3 and PI3K/AKT signaling pathways, thus promoting cancer migration and metastasis." (PMID 30563531, 2018). "By directly interacting with phosphorylated STAT3, PIAS3 can block the downstream transcriptional activity of STAT3, which is hyper‐activated in various cancers." (PMID 30259640, 2018). "These four pathways were proteoglycans in cancer (ANK2, FASLG, HSPG2, PTPN11, STAT3, and VEGFA), HIF-1 signaling (ARNT, STAT3, and VEGFA), FoxO signaling (FASLG, SMAD4, and STAT3), and ECM-receptor interaction (HSPG2 and LAMA2)." (PMID 29300322, 2018). "The IL-6/IL-6R/JAK/STAT3 is one of these pathways, which contributes to the development and progression of HNC cancers." (PMID 29951282, 2018). "In cancer cells and fibroblasts, ROCK activation induced STAT3 phosphorylation in a time frame similar to that for increased MLC phosphorylation." (PMID 30413785, 2018). "EMT can regulate the metabolic reprogramming of cancer cells by regulating the many regulatory molecules involved in EMT, including Snail, Dlx-2, HIF-1α, STAT3, TGF-β, Wnt, and Akt." (PMID 30671168, 2018). "STAT3 also displays an important role in EMT, and thus, downregulating the protein leads to reversal of EMT progress in cancer cells." (PMID 29571296, 2018). "In contrast, genes in neural (CDS1 and CHD4) and cancer-related (BTG1, COL6A1, PMP22 and HIF1A) pathways were increased by STAT3-KD, and their expression was reduced by STAT3 expression." (PMID 29774125, 2018). "In cancer, by contrast, STAT protein, especially STAT3, become activated constitutively, thereby driving the malignant phenotype of cancer cells." (PMID 29423040, 2018). "Considering the critical role of STAT3 in a variety of cancer cells, the potential therapeutic value of YL064 in other cancers warrants further investigation." (PMID 30302278, 2018). "STAT3 has been recognized a potentially promising target for therapy in ALCL and many other cancers." (PMID 29346274, 2018). "Together, these two pathways serve to upregulate a host of pro-inflammatory transcription factors, namely nuclear factor-κB (NF-κB), signal transducer and activator of transcription 3 (STAT3) and hypoxia-inducible factor 1α (HIF1α) in cancer cells." (PMID 29543710, 2018). "Pimozide has gained attention as an anti-cancer agent by acting as a STAT5 inhibitor in chronic myelogenous leukemia cells, as well as an inhibitor of STAT3 signaling pathway in hepatocellular carcinoma and suppressing cancer stem-like cell maintenance." (PMID 30405882, 2018). "STAT3, one of STAT family, is involved in cell growth and survival, inflammation, immune response, and cancer progression." (PMID 30597956, 2018). "Most importantly, through modulating the STAT3 and AKT pathways, NDRG2 can play an anti-cancer role downstream MYB/miR-130a in SACC." (PMID 30206227, 2018). "In this case, aging hypomethylated dmCpG sites tended to display a more marked enrichment of most of the cancer hypomethylation factors and, additionally, revealed the presence of other family‐ or function‐related proteins, like FOSL1/2, MAFF, MAFK, and STAT3." (PMID 29504244, 2018). "For instance, MCL1 transcription is activated by various transcription factors such as signal transducer and activator of transcription 3 (STAT3), STAT5, hypoxia-inducible factor 1 (HIF1), and E2F1 in a large variety of cancer types." (PMID 29361709, 2018). "Given that STAT3 is an important oncogenic transcription factor, and EZH2 is found to be mutated in many cancers, the interplay between these two proteins raises the possibility that targeting the STAT3-EZH2 axis might be beneficial to arrest or kill cancer cells." (PMID 29728695, 2018). "Several signaling pathways have been suggested as potential targets in cancer radioresistance including PI3K/Akt, NF-κB, TGF-β, Notch, or STAT3." (PMID 29423098, 2018).
cancer (continued). "An elevated level of IL-6 is related to cancer cell proliferation, angiogenesis, and metastasis via stimulation of MAPK, STAT3, and AKT signaling pathways." (PMID 29770167, 2018). "Higher expression levels of IL-6 have also been observed in various human cancer tissues, and IL-6 is known to induce EMT through STAT3 activation in human breast cancer cells." (PMID 29969465, 2018). "Further studies are needed to investigate the application of HEC-23 and STAT3 activation to the therapeutic treatment of AML and other cancers." (PMID 29611115, 2018). "We recently identified STAT3 (pY705) as aberrantly upregulated in a group of CLL patients and showed that STAT3 inhibitors potently kill the cancer cells." (PMID 30518828, 2018). "Cholesterol, as an essential component for lipid raft microdomains in the cellular membrane, is important for cancer growth and aggressiveness and for maintaining oncogenic growth signaling through the PI3K-AKT and STAT3 pathways." (PMID 30321984, 2018). "STAT3 is known to regulate both cell survival via BCL-256,57 and cancer progression via e.g. TWIST158." (PMID 30467386, 2018). "STAT3 is by far the most studied and best-known member of STAT family of proteins, and along with STAT5 have been extensively investigated in cancer biology." (PMID 30109213, 2018). "The Src kinase can lead to drug resistance in cancer cells during targeted therapy through the activation of several downstream effectors, particularly of AKT and STAT3." (PMID 30473665, 2018). "There is currently a need and ample room to better explore STAT3 implications in EMT, cancer stem cells and tumor resistance to therapy." (PMID 30301213, 2018). "However, formation of cancer stem-like tumorspheres was still observed in the HT29shSTAT3 cells, although STAT3 expression was downregulated, as observed using Western blot analysis, indicating that blockade of STAT3 may be insufficient to completely eradicate CRCs." (PMID 30068339, 2018). "The IL6R/gp130/STAT3 signal pathway regulates CSC renewal and cancer metastasis which leads to radiotherapy resistance." (PMID 29770167, 2018). "Several studies in different cancer types link CD44 with activation of signal transducer and activator of transcription 3 (STAT3)." (PMID 29747682, 2018). "The IL6, phosphorylated JAK2, phosphorylated STAT3 and SOX2 protein levels in 97L cancer cells were greatly elevated by SHH treatment." (PMID 29722127, 2018). "Since persistent activation of STAT3 is oncogenic and is prevalent in a wide variety of human cancers, such as CRC, we focused on the JAK2/STAT3 pathway." (PMID 30564118, 2018). "Our findings provide important insights to the mechanisms of STAT3 activation induced by the IL-6 family and identify TRIM27 as a potential therapeutic target for treatment of cancer." (PMID 30143645, 2018). "There are signaling pathways preferentially associated with cancer stem cells, including HEDGEHOG, NOTCH, STAT3, WNT/β-catenin, and NF-κB pathways that regulate stemness properties in many cancers." (PMID 30551640, 2018). "Therefore, downregulation of STAT3 may be essential for HHT-mediated anti-cancer therapy." (PMID 29844447, 2018). "KEGG pathway analysis indicated these 47 mRNAs were involved into the pathways in cancer, especially ROCK, STAT3 and SP1." (PMID 30474931, 2018). "Therefore, gastric epithelial STAT3 may contribute to cancer initiation; however, JAK/STAT signaling in gastric epithelial cells, Stat3 expression in stromal cells, and/or other signaling pathways (e.g., the JNK and NF-κB signaling pathways) may contribute to gastric tumorigenesis." (PMID 29849601, 2018). "Indeed, the chemopreventive activities of capsaicin have been hypothesized to be related to the induction of cell cycle arrest, apoptosis, or inhibition of cancer cell proliferation through antagonizing NF-κB, AP-1, signal transducer and activator of transcription (STAT3), and COX-2 expression." (PMID 29565284, 2018).